ZNF602P (zinc finger protein 602, pseudogene)
Synonyms: dJ265C24.5
Gene: Transcribed unprocessed pseudogene on chromosome 6 (28,115,628 to 28,116,551, forward strand). Ensembl gene ENSG00000219392.
Diseases named in the same sentence as ZNF602P in open-access papers:
ZNF602P is named in the same sentence as 1 disease in open-access papers, as found by Europe PMC text mining. Sharing a sentence is not in itself a finding about the gene and the disease. The quoted sentences say what the papers report.
acute appendicitis (1 paper, 2025). "Furthermore, we found that MDD and acute appendicitis have three shared genes: PRSS16, ZNF602P, and ZNF204P." (PMID 41438618, 2025). "Finally, we defined three shared genes: PRSS16, ZNF602P, and ZNF204P by TWAS and nine pleiotropic genes C4A, FLOT1, LINC00243, MICB, and PRSS16 by colocalization analysis between MDD and acute appendicitis." (PMID 41438618, 2025). "We identified three shared genes—PRSS16, ZNF602P, and ZNF204P—between MDD and acute appendicitis." (PMID 41438618, 2025).